ATF5 (activating transcription factor 5)
Description:
Transcription factor that either stimulates or represses gene transcription through binding of different DNA regulatory elements such as cAMP response element (CRE) (consensus: 5'-GTGACGT[AC][AG]-3'), ATF5-specific response element (ARE) (consensus: 5'-C[CT]TCT[CT]CCTT[AT]-3') but also the amino acid response element (AARE), present in many viral and cellular promoters. Critically involved, often in a cell type-dependent manner, in cell survival, proliferation, and differentiation. Its transcriptional activity is enhanced by CCND3 and slightly inhibited by CDK4. Important regulator of the cerebral cortex formation, functions in cerebral cortical neuroprogenitor cells to maintain proliferation and to block differentiation into neurons. Must be down-regulated in order for such cells to exit the cycle and differentiate (By similarity). Participates in the pathways by which SHH promotes cerebellar granule neuron progenitor cells proliferation (By similarity). Critical for survival of mature olfactory sensory neurons (OSN), directs expression of OSN-specific genes (By similarity). May be involved in osteogenic differentiation. Promotes cell proliferation and survival by inducing the expression of EGR1 sinergistically with ELK1. Once acetylated by EP300, binds to ARE sequences on target genes promoters, such as BCL2 and EGR1. Plays an anti-apoptotic role through the transcriptional regulation of BCL2, this function seems to be cell type-dependent (By similarity). Cooperates with NR1I3/CAR in the transcriptional activation of CYP2B6 in liver. In hepatic cells, represses CRE-dependent transcription and inhibits proliferation by blocking at G2/M phase. May act as a negative regulator of IL1B transduction pathway in liver. Upon IL1B stimulus, cooperates with NLK to activate the transactivation activity of C/EBP subfamily members. Besides its function of transcription factor, acts as a cofactor of CEBPB to activate CEBPA and promote adipocyte differentiation. Regulates centrosome dynamics in a cell-cycle- and centriole-age-dependent manner. Forms 9-foci symmetrical ring scaffold around the mother centriole to control centrosome function and the interaction between centrioles and pericentriolar material.
Synonyms: ATFX; HMFN0395
Tractability: PROTAC: UniProt records ubiquitination sites on it; ubiquitination databases record sites on it.
Gene: Protein-coding gene on chromosome 19 (49,923,910 to 49,933,935, forward strand). Ensembl gene ENSG00000169136.
Subcellular location: Cytoplasm; Nucleus; Cytoplasm, cytoskeleton, microtubule organizing center, centrosome
Subcellular location (Human Protein Atlas): Nucleoplasm; Cytosol; Vesicles
Pathways (Reactome):
Cellular responses to stimuli: Mitochondrial unfolded protein response (UPRmt); Response of EIF2AK1 (HRI) to heme deficiency
Gene Ontology:
Molecular function: chromatin binding; DNA-binding transcription activator activity, RNA polymerase II-specific; DNA-binding transcription factor activity; kinase binding; protein binding; RNA polymerase II transcription regulatory region sequence-specific DNA binding; tubulin binding; DNA-binding transcription factor activity, RNA polymerase II-specific; sequence-specific DNA binding; transcription cis-regulatory region binding
Biological process: fat cell differentiation; negative regulation of apoptotic process; negative regulation of cell cycle G2/M phase transition; negative regulation of cell population proliferation; negative regulation of DNA-templated transcription; positive regulation of DNA-templated transcription; positive regulation of transcription by RNA polymerase II; regulation of centrosome cycle; regulation of DNA-templated transcription; cerebellar granule cell precursor proliferation; regulation of transcription by RNA polymerase II; circadian rhythm; regulation of apoptotic process
Cellular component: centrosome; cytoplasm; cytosol; nucleoplasm; nucleus; RNA polymerase II transcription regulator complex; chromatin; transcription regulator complex
Genetic constraint (gnomAD): Loss-of-function variants: 11 observed, 11.26 expected, observed/expected ratio (o/e) 0.98, 90% interval 0.61 to 1.6. The synonymous counts are far from expectation, so gnomAD's model fits this gene poorly and the ratio says little. Missense variants: 401 observed, 347.87 expected, observed/expected ratio (o/e) 1.15, 90% interval 1.06 to 1.25. Synonymous variants: 193 observed, 154.45 expected, observed/expected ratio (o/e) 1.25, 90% interval 1.11 to 1.41.
Homologues: Orthologues: chimpanzee ATF5 (99% identical), macaque ATF5 (94% identical), rat Atf5 (88% identical), mouse Atf5 (88% identical), pig ATF5 (87% identical), dog ATF5 (85% identical), guinea pig ATF5 (84% identical), tropical clawed frog atf5 (51% identical), tropical clawed frog atf5.2 (51% identical), zebrafish atf5a (43% identical), zebrafish atf5b (32% identical), Caenorhabditis elegans atfs-1 (23% identical), and 1 more. Paralogues in human: ATF4 (29% identical).
Diseases named in the same sentence as ATF5 in open-access papers:
ATF5 is named in the same sentence as 105 diseases in open-access papers, as found by Europe PMC text mining. Sharing a sentence is not in itself a finding about the gene and the disease. The quoted sentences say what the papers report.
glioma (32 papers, 2010 to 2025). A benign or malignant brain and spinal cord tumor that arises from glial cells (astrocytes, oligodendrocytes, ependymal cells). "On the other hand, in glioma and breast cancer cells, ATF5 promotes EGR1 expression via its association with p300 and binding to ATF5 response elements, which contribute to the proliferation and survival of cancer cells." (PMID 40124511, 2025). "As for olfaction, a newly discovered risk factor for accelerating the progression of glioma, detected 17 target genes that exhibited consistent downregulation after naris occlusion; among them, ATF5 and FOSL2 were negatively correlated with GNAL." (PMID 38686055, 2024). "This reagent, designated ATF5-CaP-rHDL, significantly reduced the viability and caused apoptotic death of cultured rat C6 glioma cells and patient-derived glioblastoma-initiating cells, but not of cultured astrocytes." (PMID 36831248, 2023). "Previous studies have shown that ATF5 loss-of-function induces glioma cell death in culture and in vivo." (PMID 27590508, 2016). "Interference with ATF5 function in vivo causes cell death and tumor shrinkage of C6 glioma." (PMID 32603335, 2020). "ATF5 is reported to be highly expressed in pancreatic cancer, glioma, breast cancer, lung cancer, prostate cancer, and colon cancer, among others." (PMID 40124511, 2025). "ATF5 is also highly expressed in a variety of cancer types, such as glioma, breast cancer, lung cancer, and others." (PMID 38445960, 2024). "One of the genes from this heatmap was ATF5, a critical apoptosis transcription factor with implications in glioma, which we explore below." (PMID 38445960, 2024). "To confirm the differences in ATF5 expression observed in TCGA data and our MeRIP-seq hypermethylation data, we performed targeted qRT-PCR on RNA isolated from fresh frozen glioma tumor samples obtained through the UCLA Brain Tumor Translational Resource." (PMID 38445960, 2024). "Similar to our data, ATF5 expression has been shown to be inversely correlated with patient overall survival in glioma." (PMID 38445960, 2024). "Median ATF5 mRNA expression for the cohorts was log2 8.36 in IDH1mut gliomas (SD = 0.66), and log2 9.54 in IDH1wt gliomas (SD = 0.80), and lower ATF5 expression was correlated with survival benefits in both IDH1mut and IDH1wt glioblastomas (log rank P < 0.05)." (PMID 38445960, 2024). "Future studies are necessary to demonstrate the role of ATF5 downregulation in the indolent phenotype of IDH1mut gliomas, as well as to identify other involved gene transcripts deregulated by m6A hypermethylation." (PMID 38445960, 2024). "These important findings thus indicate that ATF5 can drive survival of glioma cells as well as resistance to conditions or treatments that can otherwise promote apoptotic death." (PMID 36831248, 2023). "While 15/16 control animals in which DN-ATF5 was turned off at the time of tumor induction developed tumors that expressed GFAP and ATF5, only 1/7 animals in which DN-ATF5 was on at the time of tumor induction developed a glioma." (PMID 36831248, 2023). "The canine study cited above also showed by WB significant elevation of ATF5 protein in gliomas compared with normal brain tissue." (PMID 36831248, 2023). "For example, ATF5 regulates Egr-1 expression in glioma and breast cancer cells to mediate proliferation and survival." (PMID 35864539, 2022). "Due to the promotive role of ATF5 in cancer, ATF5 expression is positively correlated with cancer progression in epithelial ovarian carcinomas and glioma." (PMID 35180892, 2022). "For example, the methylation level in the promoter region of the ATF5 gene in glioma is significantly reduced compared with that in normal tissues." (PMID 35180892, 2022). "This replaces the interaction of the ATF5 protein with heat-shock protein 70 (HSP70), which maintains high levels of ATF5 expression by preventing its degradation in glioma cells." (PMID 35806136, 2022).
glioma (continued). "ATF5 is highly expressed in most cancers, including myeloid leukemia, glioma, breast, ovarian, lung, colorectal, gastric, rectal, and pancreatic cancer." (PMID 35806136, 2022). "In this process, the down-regulation of ATF5 expression by miR-141-3p inhibits cell proliferation and promotes cell apoptosis in gliomas." (PMID 35806136, 2022). "DNA methylation in the ATF5 promoter region was decreased, and ATF5 mRNA expression was elevated in glioma tissues compared with normal tissues." (PMID 35805170, 2022). "Some examples include inhibiting PRMT1/ATF5 in neuroblastomas, increasing the level of ATF5 inhibition-related miRNAs in gliomas, targeting the Fis-1/ATF5 axis in metabolic diseases, or targeting ATF5 in diabetes." (PMID 35806136, 2022). "Studies have shown that HCMV enhances the expression of anti-apoptotic activating transcription factor 5 (ATF5), which is extensively upregulated in glioma cells and contributes to their survival." (PMID 35515137, 2022). "In a variety of cancers, ATF5 has also been characterized to be upregulated, such as leukemia, breast cancer and gliomas." (PMID 34895217, 2021). "The methylation level of ATF5 has been reported to be different in poorly differentiated glioma, well-differentiated glioma, and normal tissues, which suggested that aberrant methylation of ATF5 is connected with the pathophysiology of glioma." (PMID 34136553, 2021). "When ATF5 function is blocked or silenced in vitro, apoptosis occurs in a number of cancer cells such as C6 glioma, SKOV-3 ovarian cancer, MCF-7, and other breast cancer cell lines, but not in non-transformed cells." (PMID 32603335, 2020). "Recently, miR-141-3p was found to inhibit ATF5 protein synthesis and lead to a decrease in tumor size in vivo in glioma." (PMID 32603335, 2020). "Of the cancers with which the role of ATF5 has been investigated, gliomas have been the most extensively studied." (PMID 29137451, 2017). "Here we showed that HCMV IE protein does form complexes with endogenous ATF5, which in turn enhances the acetylation of ATF5 that promoting glioma cell survival." (PMID 28473657, 2017). "In C6 glioma cells, following the treatment with ATF5-CaP-rHDL for48 h, the expression of ATF5 mRNA and protein was reduced by75–85%." (PMID 28489075, 2017). "The mechanisms which ATF5 promotes cell survival have been well studied in gliomas relative to other cancer types." (PMID 29137451, 2017). "Similar to the pattern we observed for IE86 expression, we found ATF5 protein high expression in tumor nucleus and cytoplasm of glioma tissues than normal tissues." (PMID 28473657, 2017). "Interference with ATF5 function by transient transfection of a dominant-negative elicited an apoptotic response in glioma cell lines but spared astrocytes, though astrocytes ectopically expressing dnATF5 exited the cell cycle." (PMID 29137451, 2017). "In this study, we highlighted the relationship of two important regulator proteins, IE and ATF5, in regulating the glioma cells survival under HCMV infection." (PMID 28473657, 2017). "The IE protein and ATF5 all express in glioma tissue and cell line and both of them can form complexes with p300." (PMID 28473657, 2017). "Here we report the relationship among HCMV infection, glioma classification and ATF5 expression in paraffin sections of surgically excised glioma tumors." (PMID 28473657, 2017). "Activating Transcription Factor 5 (ATF5) is highly expressed in gliomas, and interference with its expression/function precipitates targeted glioma cell apoptosis in vitro and in vivo." (PMID 26863637, 2016).
glioma (continued). "In revealing the anti-apoptotic mechanism of ATF5 in HCMV-infected glioma, it was found that Bcl-2 was downregulated in the U87 cells in which ATF5 was inhibited, when compared with the control." (PMID 25120656, 2014). "ATF5 is an anti-apoptotic protein that is highly expressed in malignant glioma and is essential for glioma cell survival." (PMID 25120656, 2014). "The high expression of ATF5 in brain tumors, combined with the fact that it is selectively essential for glioma cell survival, make ATF5 an appealing potential therapeutic target for the treatment of malignant glioma." (PMID 21311102, 2010). "Additionally, miR-141-3p suppresses glioma growth by targeting and inhibiting the antiapoptotic factor ATF5." (PMID 40407536, 2025). "Moreover, that ATF5 contributes to cancer progression is further evidenced by its suppression of apoptosis in glioma and breast cancer cells, promotion of metastasis in neuroblastoma cells, and enhancement of drug resistance in pancreatic cancer cells." (PMID 40124511, 2025). "In exploring downstream effectors of our proposed IDH1mut → D-2-HG ⊣ FTO axis using bioinformatic and biologic experiments, we identified ATF5 (an oncogenic protein involved in proliferation and suppression of apoptosis) as a mediator of glioma growth inhibition." (PMID 38445960, 2024). "In addition, high ATF5 expression correlates with reduced survival in glioma and lung cancer patients." (PMID 36768800, 2023). "In addition to human and rodent tumor cells, ATF5 expression has also been examined in canine gliomas." (PMID 36831248, 2023). "ATF5 protein expression in gliomas has also been evaluated by Western immunoblotting (WB)." (PMID 36831248, 2023). "In a different role, ATF5 has been described as an evolutionarily conserved mediator of the mitochondrial unfolded protein stress response that is postulated to play a protective role in glioma and other cancer cells." (PMID 36831248, 2023). "On the other hand, there appears to be a divergence in findings as to whether there is over-expression of ATF5 protein and mRNA in lower-grade gliomas." (PMID 36831248, 2023). "Given the over-expression of ATF5 in GBM and potentially lower-grade gliomas, several groups have queried whether ATF5 levels correlate with patient survival." (PMID 36831248, 2023). "Besides promoting cancer growth via recovery of mitochondrial functions, ATF5 has also been shown to promote proliferation and survival of glioma and breast cancer cells by regulating Egr-1 expression." (PMID 36768800, 2023). "Similarly, in gliomas, overexpression of HSP70s greatly maintains the stability of activating transcription factor 5 (ATF5), preventing its degradation through protease-dependent and caspase-dependent processes." (PMID 38062023, 2023). "HSP70 promotes survival of C6 and U87 glioma cells by inhibition of ATF5 degradation." (PMID 35928554, 2022). "High ATF5 expression correlates with reduced survival in glioma and lung cancer patients." (PMID 35864539, 2022). "Furthermore, HCMV infection can trigger miR-134-5p down-regulation, which is the negative regulator of ATF5 expression, thus, resulting in high levels of ATF5 and increased glioma cell survival." (PMID 35806136, 2022). "ATF5 transactivates BCL-2 in glioma and breast cancer cells to promote survival." (PMID 35864539, 2022). "Indeed, upon analyzing the expression levels of ATF5 in a variety of cancer types it is evident that ATF5 expression is highly upregulated in various forms of cancer such as glioma, breast cancer, lung cancer, and numerous others." (PMID 29137451, 2017). "In addition, ATF5 was shown to mediate the survival response to serum deprivation and staurosporine treatment in C6 glioma cells supporting the notion that ATF5 has an oncogenic and prosurvival role in gliomas." (PMID 29137451, 2017).